EGFR (epidermal growth factor receptor)
Diseases named in the same sentence as EGFR in open-access papers (continued):
Sharing a sentence is not in itself a finding about the gene and the disease.
cancer (continued). "Since the altered signaling of both Netrin-1 and EGFR plays a widespread role in cancer, we examined whether the two proteins might be functionally connected." (PMID 27031829, 2016). "In contrast with this observation, others indicate that intra-cellular trafficking of EGFR is enhanced by Cetuximab and there is a wide literature correlating poor response to Cetuximab with EGFR nuclear localization thus making nuclear EGFR an important molecular target in cancer." (PMID 26575422, 2016). "EGFR is dysregulated in several malignant tumors located in head and neck, esophageal, gastric, lung, colorectal, and other organs, which correlates with increased metastasis, decreased survival, a poor prognosis and radiotherapy (RT) and chemotherapy (CT) resistance." (PMID 27050148, 2016). "Anti-EGFR-targeted therapy has become an important aspect of cancer treatment in recent years." (PMID 27955638, 2016). "This may in turn account for the relationship between CDCP1 or EGFR expression in cancer and increased invasiveness, elevated cancer dissemination, and poor patient outcome." (PMID 27495374, 2016). "This new signaling function of PLD-PA targeting EGFR trafficking and biphasically modulating its transcription, could explain cell proliferation initiation and its maintenance in cancer cells." (PMID 27256981, 2016). "EGFR is an oncogenic receptor tyrosine kinase, and has a broad of biological functions implicating in cellular proliferation, metastasis, angiogenesis, and chemo/radioresistance of cancer cells." (PMID 27417393, 2016). "However, as GPCRs have also been shown to stimulate cancer cell proliferation in an-EGFR independent pathway, the observed synergism cannot be convincingly attribute to the role of EGFR transactivation by GPCR." (PMID 26771606, 2016). "EGF-EGFR Cancer cells express 2 − 3 × 106 EGFR proteins per cell." (PMID 28002496, 2016). "DNA fragments can even be detached from chromosomal DNA and propagated as so-called ‘double minute chromosomes’ whose abundance can change rapidly, for example, to maintain optimal epidermal growth factor receptor (EGFR) signaling levels during cancer drug therapy." (PMID 26949746, 2016). "The modestly activated non-mutated EGFR has anyways a role in cancer promotion by the induction of cell proliferation, apoptosis inhibition, angiogenesis, cellular motility and invasiveness." (PMID 26993607, 2016). "The activation of AXL contributes to resistance to EGFR-TKI in multiple types of cancers." (PMID 27590506, 2016). "Conversely, the use of EGFR antagonists in cancer treatment may accelerate the effects of Aging Proper in the brain and other organs." (PMID 27922822, 2016). "Similarly, EGFR blockade dramatically enhanced the apoptosis of cancer cells induced by ultraviolet radiation and chemotherapeutic agents." (PMID 27888617, 2016). "One hypothesis for the mechanism underlying ANO1′s channel-independent function in promoting EGFR-signaling and cell proliferation is that ANO1 exhibits its function in cancer cells by interacting with membrane proteins." (PMID 25823819, 2015). "Knockdown of ANO1 inhibits EGFR-signaling in cancer cells, by a yet undefined mechanism." (PMID 25823819, 2015). "In cancer, the combination of erlotinib and alisertib was first suggested by an siRNA screen that identified genes that influenced cellular response to inhibition of EGFR." (PMID 26528438, 2015). "However, the molecular mechanisms underlying EGFR signaling-triggered EMT and cancer progression remains largely unclear and must be further investigated." (PMID 26307676, 2015). "Future studies and identification of such repressors could lead to novel treatments that inhibit EGFR in cancer." (PMID 25959250, 2015). "Activating mutations in EGFR and BRAF are frequently found to be associated with cancer." (PMID 26518340, 2015).
cancer (continued). "In our study, we demonstrated that using the BEAMing technology, testing for 21 oncogenic mutations in BRAF, EGFR, KRAS and PIK3CA genes in the plasma cfDNA of patients with advanced cancers referred for treatment with experimental targeted therapies, is feasible." (PMID 25980577, 2015). "It is known that cisplatin can activate epidermal growth factor receptor (EGFR), which may provide a survival benefit in cancers." (PMID 26568478, 2015). "To prove this hypothesis, we investigated the effects of HSP90 blockade on functionality and expression of EGFR in cancer cells." (PMID 25590805, 2015). "EGFR is overexpressed or overactive in most cancers of epithelial origin." (PMID 26378037, 2015). "Thus, targeting EGFR to turn off its signal transduction is envisaged to block growth and survival of cancer cells." (PMID 25789858, 2015). "Therefore, the inhibition of LeY synthesis and LeY mediated activation of EGFR/MAPK signaling pathway play an important role in the treatment of cancer." (PMID 25672851, 2015). "Several genomic rearrangements leading to oncogenic C-terminal deletion mutant EGFR have been identified in cancer, however the molecular mechanisms mediating cellular transformation by these oncogenic mutants is unknown." (PMID 25826094, 2015). "Studies in this laboratory have demonstrated that basal expression of genes, such as survivin, VEGF and EGFR, in various cancer cell lines is dependent on specificity protein (Sp) transcription factors Sp1, Sp3 and Sp4 which are highly expressed in many cancer cells and tumors." (PMID 26673922, 2015). "Moreover, further biomolecular examination is necessary to evaluate correlations between the 3 EGFR statuses and cancer cell invasiveness." (PMID 26496308, 2015). "The observation that the overexpression of both sialidase NEU3 and EGFR occurs in various human cancers suggested that they might functionally interact and contribute to cancer progression in a synergistic manner." (PMID 25803810, 2015). "In fact, discontinuation of EGFR-TKI therapy in patients who were once sensitive to EGFR inhibition may lead to more rapid cancer progression 63,64." (PMID 26310719, 2015). "Thus, targeting of NPs to EGFR by grafting EGF or anti-EGFR agents is a good alternative for cancer treatment." (PMID 28347103, 2015). "Sequence and functional optimization of EGFR mimetic peptides may be useful for the development of novel cancer drugs addressing EGFR overexpression in tumors." (PMID 26835447, 2015). "Additionally, EGFR was strongly expressed in the edges of the cancer nests in the three subtypes of AdCC." (PMID 25997612, 2015). "In this study, we analyzed mitochondria protein composition of NSCLC cells with different invasive abilities, and found that EGFR is one of the candidates which may influence cancer invasion." (PMID 26497368, 2015). "Overall, these results supported the view that the PC-PLC activity could affect the EGFR signaling in the A431 cancer cells and have an impact on the mechanisms of MAPK- and AKT-mediated cell signaling cascades." (PMID 26402860, 2015). "To test whether EGFR-signaling regulates ANO1-expression in cancer cells, we generated Te11 cells stably expressing a dox-inducible version of EGFR or lz-EGFR (Te11-EGFR, Te11-lz-EGFR)." (PMID 25823819, 2015). "In addition, Iran still faces challenges regarding the access to anticancer medicines, especially costly anti-EGFR-targeted cancer therapy protocols." (PMID 25685149, 2015). "Thus, SOX2 induction isconsistently observed following acute withdrawal of EGFR signals in cancer models aswell as in patient-derived cells that exhibit oncogene dependence on the EGFRpathway." (PMID 25686219, 2015). "Furthermore, EGFR is one of the major cancer-related signaling molecules to be controlled by miRNAs." (PMID 26090723, 2015).
cancer (continued). "EGFR cooperates with STAT3 to induce EMT in cancer cells via increasing Twist gene expression." (PMID 25915156, 2015). "Over-expression of EGFR is frequently found in epithelial cancers and correlated with clinical aggressiveness and poor outcome, suggesting that targeting EGFR is an important strategy for cancer treatment." (PMID 25980579, 2015). "Early research suggested that blocking EGFR/HER1 by its specific inhibitor may have activity in some cancers through tyrosine kinase signaling inhibition." (PMID 25674538, 2015). "The EGFR kinase inhibitors erlotinib and lapatinib have been used in cancer therapy." (PMID 25999657, 2015). "However, anti-EGFR-TK therapy using gefitinib, erlotinib, or cetuximab produces different results in different human cancers." (PMID 25950441, 2015). "This study suggests that the presence of t-Darpp in HER2+ cancers might predict the enhanced response to dual HER2/EGFR targeting." (PMID 26121470, 2015). "In support of these findings, treatment with ART down-regulated the expression of multiple molecules associated with maintaining cancer stemness and metastatic potential, including c-MYC, epidermal growth factor receptor (EGFR), c-MET, Src, and focal adhesion kinase (FAK)." (PMID 26426994, 2015). "A number of second-generation EGFR inhibitors, most of which are irreversible, inhibit two or more receptors in the EGFR family, and may have some activity in T790M-mutant cancers, have been evaluated in clinical trials." (PMID 26134262, 2015). "The molecular mechanisms underlying radiosensitization of cancer cells following EGFR inhibition is not completely clear, as it varies with the tissue of origin." (PMID 26546517, 2015). "However, the molecular mechanism by which EGFR signaling regulates cancer cell metabolism is still unclear." (PMID 26023239, 2015). "The expression of epidermal growth factor receptor (EGFR/ERBB1/HER1) is implicated in the progress of numerous cancers, a feature that has been exploited in the development of EGFR antibodies and EGFR tyrosine kinase inhibitors as anti-cancer drugs." (PMID 25622307, 2015). "Hence, it was suggested that the subset of side population cells in the heterogeneous cancer cell population was resistant to EGFR TKIs." (PMID 25871388, 2015). "Src activation is involved in cancer progression and the interplay with EGFR." (PMID 26312766, 2015). "Because K-RAS mutation (G12S) and EGFR amplification were detected in A549 cells, the effects of serum depletion were first considered to be related to the MAPK signaling cascade which is also known to play an important role in proliferation of cancer." (PMID 26167183, 2015). "Fortunately, EGFR signal pathway can be blocked by small-molecule tyrosine kinase inhibitors (TKIs), including gefitinib and erlotinib, which targeting the EGFR to suppress cancer cell proliferation, invasion and metastases." (PMID 26057469, 2015). "EGFR expression and low rates of and mutations support further investigation of anti-EGFR therapies for this cancer type, noting that expression of EGFR has not been universally correlated to therapeutic effect of targeting across all cancer types." (PMID 26498363, 2015). "EGFR is recognized as oncogenic driver in tumorigenesis and a target for cancer therapies." (PMID 26538117, 2015). "In addition, Src has been reported to interact with EGFR; these proteins phosphorylate each other, and cellular Src and EGFR collaborate in cancer progression." (PMID 25955608, 2015). "However, many clinical trials have demonstrated that anti-angiogenic agents enhanced clinical efficacy when combined with conventional chemotherapy or targeted cancer agents such as erlotinib, an epidermal growth factor receptor (EGFR) TKI." (PMID 26401847, 2015). "EGFR was found amplified in 7 of 109 cancers (6.4%) in at least one TMA spot." (PMID 25649416, 2015). "By degradation of EGFR, WJ exerted promising anti-cancer effect like cisplatin." (PMID 25980579, 2015).
cancer (continued). "This mutator phenotype could facilitate the acquisition of additional driver mutations in alternative proliferation or survival pathways, and enable cancer cells to become resistant to EGFR-targeting therapies." (PMID 25823662, 2015). "EGFR is a well described target of miR-7, is a prominent regulator of normal cell differentiation, development and proliferation, and is commonly targeted for therapy in cancer." (PMID 26308064, 2015). "Inhibits EGFR, can stimulate apoptosis and differentiation of cancer cell that lack EGFR." (PMID 25588753, 2015). "Similarly, YAP upregulation of EGFR through a YAP–TEAD complex at the EGFR promoter has been shown to partly explain the reduced translational impact of EGFR inhibitors in cancer." (PMID 26389076, 2015). "And because of that, the combined use of SFK inhibitors like Dasatinib and EGFR inhibitors might also exert synergistic or additive effects in cancer treatments." (PMID 26061184, 2015). "EGFR was identified as an important oncogenic factor in several cancer types." (PMID 25991665, 2015). "Among these miRNAs, miR-7 has been demonstrated to downregulate EGFR in different cancer cells." (PMID 26273639, 2015). "Because the EMT process can be regulated by a diverse array of cytokines and growth factors, we analyzed the activation status of several kinases and their effectors involved in cancer cell proliferation and survival, including EGFR, IGF-1R, Src, FAK, Akt, Erk1/2, mTOR, MEK1/2, and p70S6K." (PMID 26416450, 2015). "Honokiol targets multiple signaling pathways such as nuclear factor κB (NF-κB), signal transducers and activator of transcription 3 (STAT3), mammalian target of rapamycin (mTOR) and epidermal growth factor receptor (EGFR), which have great relevance during cancer initiation and progression." (PMID 25846316, 2015). "Given that PI3K/mTOR inhibitors repress aerobic glycolysis in EGFR-mutated LAD cells, further studies are warranted to understand how cancer cell metabolism is regulated and to develop more effective therapeutic agents specifically targeted to the metabolic pathways that can limit cancer growth." (PMID 26023239, 2015). "Thus, inhibiting EGFR in conjunction with STATs would be a promising and attractive therapeutic strategy for cancers." (PMID 26106437, 2015). "Both HER2 and EGFR have importance in cancer biology, however." (PMID 26143491, 2015). "The mechanisms relating matrine and oxymatrine to axonal growth remain unknown, although antagonistic activities of those compounds on epidermal growth factor receptor (EGFR) were shown in relation to anti-cancer effects." (PMID 26834638, 2015). "Several known cancer-related genes, including EGFR and CDKN2A/2B, are harbored in these regions." (PMID 26386145, 2015). "Mutant forms of EGFR have different trafficking compared with the wild type receptor, since some of the regulatory proteins that balance the EGFR pathway present altered expression in cancer." (PMID 26308162, 2015). "To perform these analyses, we amassed a collection of 11 EGFR mutant cancer samples (from nine patients) that underwent transformation to SCLC at the time of acquired resistance to EGFR TKI therapy under the auspices of an institutional review board (IRB)-approved protocol." (PMID 25758528, 2015). "In addition, fibronectin, matrix metalloproteinase-9 (MMP9) and E-cadherin were essential components in EGFR/PTX3-mediated cancer metastasis." (PMID 25797258, 2015). "Similarly to our results, other studies in cancer samples revealed a correlation between nuclear EGFR localization and Cyclin D1 expression." (PMID 25991665, 2015). "In an independent study, FAK and EGFR, which are overexpressed in cancer, were significantly higher in MVs from BrCa patients compared to healthy donors and were found to be differentially expressed depending on the stage of cancer." (PMID 26601108, 2015). "Understanding naturally-occurring ways of downregulating EGFR in cancer cells was investigated." (PMID 26493292, 2015).
cancer (continued). "However, most anti-EGFR-targeted agents fail to repress cancer progression because of developing drug-resistance." (PMID 26273639, 2015). "Moreover, the combined treatment of celecoxib with AEE788 had a greater impact on cancer cell migration in agreement with previous studies suggesting crosstalk between EGFR and COX-2." (PMID 26107817, 2015). "Despite early responses to EGFR-TKIs, cancers develop resistance after around 10 months of therapy." (PMID 25871388, 2015). "Similarly, in BRAF mutantcolorectal cancers, feedback activation of EGFR-dependent signaling attenuates theconsequences of mutant BRAF inhibition, suppressing the apoptotic effect." (PMID 25686219, 2015). "Clarifying the regulation of miRNAs by erlotinib may indicate novel strategies for enhancing EGFR-targeted cancer therapy." (PMID 26593208, 2015). "Finally, several trials have combined insulin/IGF-targeting drugs with EGFR inhibitors in a number of different cancers based on pre-clinical studies showing that EGFR signaling mediates resistance to IGF-IR inhibition and vice versa." (PMID 26029167, 2015). "Serglycin is secreted in elevated levels in cancer cells mutated in KRAS or HER1/EGFR, the fact that may suggest an implication of EGFR-RAS pathway in the biosynthesis and more importantly in secretion of serglycin." (PMID 26581653, 2015). "We first screened a panel of NSCLC cancer cell lines and found that only mutant EGFR-expressing cell lines, such as H3255 (EGFR L858R, GI50: 0.11 μM), PC-9 (EGFR Del 19, GI50: 0.05 μM), and HCC827 (EGFR Del 19, GI50: 0.063 μM), are sensitive to ibrutinib treatment." (PMID 26375053, 2015). "Both EGFR and Notch signaling are known to be deregulated in many human cancers." (PMID 25996086, 2015). "Our data, along with previous research, demonstrating that activation of MAPK pathways promote survival of cancer cells suggest that co-culture with fibroblasts partially abrogates the gefitinib-induced inhibitory effect of downstream molecules in an EGFR-independent manner in HCC827 cells." (PMID 25634113, 2015). "The DDA pharmacophore may also find more widespread use in drug development beyond the treatment of HER2- and EGFR-driven human cancers." (PMID 25865227, 2015). "MUC1 was also described to modulate TGF-α-dependent cancer progression and to regulate EGFR stability upon activation and might induce transformation through the inhibition of EGFR degradation." (PMID 26729094, 2015). "Our findings may help create a foundation to better understand and improve current anti-EGFR therapies for the treatment of cancer." (PMID 26568478, 2015). "Moreover these cancers are consistently wild-type EGFR which on itself precludes significant therapeutic efficacy from single EGFR inhibition." (PMID 25992771, 2015). "We developed a novel mass spectrometry multiplexed genotyping platform named PentaPanel to concurrently assess single nucleotide polymorphisms in 56 hotspots of the 5 most clinically relevant cancer genes, KRAS, NRAS, BRAF, EGFR and PIK3CA for a total of 221 detectable mutations." (PMID 26435479, 2015). "Besides EGFR-TKIs targeting EGFR protein, various kinds of small molecule compounds have been developed to target cancer-specific molecular alterations." (PMID 26090892, 2015). "Careful evaluation will be further required in these other EGFR-related cancer types." (PMID 25730907, 2015). "Moreover, the activation of epidermal growth factor receptor (EGFR) signaling pathway induces cancer cell EMT via STAT3-mediated Twist gene expression." (PMID 25915156, 2015). "Epidermal Growth Factor Receptor (EGFR) is a well-characterized cancer drug target." (PMID 25880749, 2015). "Currently, for the role of miRNAs in EGFR-targeted cancer therapy is unclear." (PMID 26593208, 2015).